PAX2 (paired box 2)
Diseases named in the same sentence as PAX2 in open-access papers (continued):
Sharing a sentence is not in itself a finding about the gene and the disease.
kidney disease (15 papers, 2011 to 2025). "The findings highlight the association between PAX2 mutations and early-onset kidney disease with potential extrarenal involvement." (PMID 40948392, 2025). "Both Patient 2 and 3 were found to carry a heterozygous PAX2 gene pathogenic variant NM_000278.5:c.250G>A, NP_000269.3:p.(Gly84Ser), rs2133836340, confirming the genetic cause for their kidney disease." (PMID 40282888, 2025). "According to the literature, 92% of individuals with PAX2 gene variants have kidney disorders, while 77% present with ophthalmologic diseases." (PMID 40282888, 2025). "The inclusion criteria were as follows: cohort studies, case-control studies, narrative reviews, systematic reviews, human studies, PAX2-mutation-associated kidney disorders, and PAX2 in pediatric patients." (PMID 37628926, 2023). "This research included an analysis of reported PAX2 mutations, case reports of kidney disorders linked to PAX2 and studies looking into the prevalence of PAX2 genes in populations with kidney disease." (PMID 37628926, 2023). "There was a considerable history of renal disease on the father’s side of the family, which was described by a novel pathogenic variant in the PAX2 gene." (PMID 37628926, 2023). "Lately, substantially more reported mutations in PAX2 have been found in renal disorders exclusively." (PMID 37628926, 2023). "Here we analyzed PAX2 pathogenic variants from the Chinese Children Genetic Kidney Disease Database (CCGKDD) which has assembled the largest genetically screened cohort with childhood kidney disease in China to date." (PMID 34696790, 2021). "In the available literature, we found that 90 reported pathogenic variants in PAX2 from 234 patients with kidney disease." (PMID 34696790, 2021). "We found that four novel variants may contribute to the development of kidney disease by impairing PAX2’s ability to regulate cell proliferation." (PMID 40948392, 2025). "We hypothesize that the mechanism underlying the development of kidney disease in patients with these PAX2 mutations may involve a weakened ability of PAX2 to regulate cell proliferation." (PMID 40948392, 2025). "The inclusion of PAX2 gene in targeted next-generation sequencing (NGS) gene panels for kidney diseases allows for the identification of disease-causing variants, even in cases where clinical diagnosis may not be accurate." (PMID 40282888, 2025). "Our review focuses on pediatric renal disorders associated with PAX2 mutations." (PMID 37628926, 2023). "Considering that PAX2 mutation frequency seems to be underestimated when treating patients who have CAKUTs, chronic kidney illnesses with no known cause, the involvement of several systems, and/or family histories of renal disease, clinicians need to be vigilant and look for the PAX2 mutation." (PMID 37628926, 2023). "Variants in PAX2 gene described in pediatric patients with renal disorders." (PMID 37628926, 2023). "Some reports found that the expression of PAX2 was closely associated with some kidney diseases." (PMID 22949832, 2012). "Due to variable expressivity, a wide range of clinical manifestations of rare hereditary kidney diseases are still underdiagnosed, and a multidisciplinary approach is required to detect extrarenal signs of PAX2-related disorder." (PMID 40282888, 2025). "In parallel, Pax2- and Pax8-positive LPM progenitors form the kidney, as initially discovered by the contribution of Pax2/8 perturbation to kidney disease." (PMID 37125615, 2023). "Because of the high prevalence of renal diseases, especially CAKUTs, in pediatric patients and their significant impact on patients’ quality of life and lifespan, we point out that patients with kidney disorders of unknown cause should be tested for PAX2 mutations." (PMID 37628926, 2023). "A total of 32 probands of PAX2-related disorder were enrolled in this study of 2256 affected individuals with a wide spectrum of kidney diseases on CCGKDD from 2014 to 2020." (PMID 34696790, 2021).
kidney disease (continued). "The present work summarizes pediatric patients found to have mutations in the PAX2 gene related to kidney disease without the involvement of other organs." (PMID 37628926, 2023). "Compared with the patients with other hereditary kidney diseases, patients with PAX2 variants develop KF mainly in adolescence rather than in infancy or childhood." (PMID 35444690, 2022). "Several groups have found that PAX2 expression closely correlates with various kidney diseases." (PMID 30117015, 2018). "The five genes COL4A5, COQ8B, NPHP1, PAX2, and WT1 accounted for 66.9% of the monogenetic kidney disease diagnoses." (PMID 39363361, 2024).
infection (4 papers, 2021 to 2024). The state of being infected such as from the introduction of a foreign agent such as serum, vaccine, antigenic substance or organism. "The specific expression levels of Pax2, Pax8, Eya1, Six1, and Dlx5 in cells from the J1-6d infection scheme were significantly lower than those in the cells infected with NC-shRNA, as shown by semi-quantitative RT-PCR (p < 0.01)." (PMID 34940631, 2021). "Further, the percentage of Pax8/Pax2 double-positive cells in the J1-6d infection scheme was significantly lower than that of cells infected with NC-shRNA, as shown by immunostaining with specific antibodies (Figure 2C1,C2)." (PMID 34940631, 2021). "Browne and colleagues reported the downregulation of PAX2 in CMV-infected primary fibroblasts at 1 and 48 h post infection." (PMID 33419104, 2021). "However, we can essentially rule out this possibility because following infection by GFAP-GFP AAVs, there were no GFP+ cells present in the GCL that co-localized with either Pax2, Sox9, GFAP, or S100β which are astrocyte markers." (PMID 34671605, 2021).
neurodevelopmental disorder (4 papers, 2021 to 2025). A behavioral and cognitive disorder with onset during the developmental period that involves impaired or aberrant development of intellectual, motor, or social functions. "Patients with Pax2 mutations exhibit various neurodevelopmental disorders, such as ASD, epilepsy, intellectual disability, and developmental delay." (PMID 37786962, 2024). "Nevertheless, several transcription factor motifs were proximate to the CpGs identified across tissue types, including the PAX (paired box; PAX2/5/9) transcriptional regulators, whose mutations are associated with multiple neurodevelopmental disorders." (PMID 38808605, 2024). "The protein that is encoded by Pax2 has been implicated in the development of the nervous system and neurodevelopmental disorders." (PMID 37786962, 2024). "The role of BDNF in Pax2-lineage descendants in lower hindbrain regions thus needs to be revisited in the context of neurodevelopmental disorders, such as autism spectrum disorder (ASD)." (PMID 33841098, 2021). "The role of Pax2-lineage descendants in brain function, particularly for higher brain function or neurodevelopmental disorders, is elusive." (PMID 33841098, 2021).
adenocarcinoma (3 papers, 2021 to 2025). A common cancer characterized by the presence of malignant glandular cells. "The 2/29 PAX2 nonaberrant adenocarcinomas (PAX2 expressors) had been clinically tested for mismatch repair (MMR) deficiency by IHC; both retained expression of all 4 MMR markers." (PMID 39078313, 2025).
immune diseases (2 papers, 2022 to 2026). "As a transcription factor, PAX2 has not been reported to be involved in the pathogenesis of immune diseases." (PMID 35444690, 2022).
kidney (2 papers, 2022 to 2023). "For instance, a case reported by our group suggested that PAX2 could act as a modifier gene in the Nail Patella phenotype." (PMID 36835576, 2023).
gynecologic tumors (1 paper, 2025). "Our study demonstrated that PAX2 and PAX8 were more upregulated in MLAs than in conventional gynecologic tumors and were enriched in mesonephric tubule morphogenesis." (PMID 40740763, 2025).
retinopathy (1 paper, 2023). "Upon querying a single cell RNA‐seq dataset, we showed pax2 highly expressing cell types clustered with early progenitor cells.Therefore, there remains the possibility that interplay between PAX2/6 and YAP1 influences the proliferative state seen in CRB1 retinopathy." (PMID 36656098, 2023).
urinary tract disorders (1 paper, 2023). "From what we know so far from the literature, this is the first review gathering pediatric patients presenting the PAX2 mutation who have been diagnosed exclusively with renal and urinary tract disorders." (PMID 37628926, 2023).
PAX2 also shares sentences with these, for which no sentence is quoted: Anophthalmia (4 papers); polycystic kidney disease (4); Townes-Brocks Syndrome 1 (4); Baraitser-Winter syndrome (3); colon cancer (3); Duane-radial ray syndrome (3); abnormalities of the kidney (2); aniridia (2); cryptorchidism (2); end stage renal disease (2); glomerulopathies (2); hyperuricemia (2); kidney tumors (2); maturity-onset diabetes (2); nail-patella syndrome (2); nephronophthisis (2); Nystagmus (2); Obesity (2); sarcoma (2); synovial sarcoma (2); viral infection (2); adenocarcinomas of the ovary (1); albuminuria (1); amblyopia (1); amyotrophic lateral sclerosis (1); angiomyolipoma (1); APRT deficiency (1); atrial fibrillation (1); atypical endometrial hyperplasia (1); autosomal dominant tubulointerstitial kidney disease (1).
A further 69 diseases each share a sentence with PAX2 in 1 paper.